MOG (myelin oligodendrocyte glycoprotein)
Diseases named in the same sentence as MOG in open-access papers (continued):
Sharing a sentence is not in itself a finding about the gene and the disease.
Stroke (24 papers, 2014 to 2025). Sudden impairment of blood flow to a part of the brain due to occlusion or rupture of an artery to the brain. "These cases were presented with stroke, myelin oligodendrocyte glycoprotein (MOG) antibody associated disorders and neuromyelitis optical spectrum disorder (NMOSD), respectively." (PMID 35360167, 2022). "If a patient with SWS develops stroke-like symptoms accompanied by abnormal CSF findings or subtentorial lesions, testing for MOG antibodies should be considered." (PMID 38292807, 2024). "Inverse variance weighted (IVW) MR analyses were performed to assess the effects of genetically predicted CA14, CDCP1, and MOG levels on cognitive function, structural brain phenotypes, and Alzheimer’s disease, and stroke." (PMID 38762535, 2024). "The use of a myelin oligodendrocyte glycoprotein (MOG) T cell receptor (TCR) transgenic (2D2) mouse model allowed for an investigation of CNS-antigen-specific lymphocyte infiltration post-stroke." (PMID 36446955, 2022). "By contrast, a male predominance was seen in stroke and other neurological disease groups, the majority of whom had low or borderline MOG-Ab ratios." (PMID 34262784, 2021). "MOG-Ab positive NMOSD, MOG-AD and ODD patients were younger than MOG-Ab positive patients in the stroke and other neurological diseases groups." (PMID 34262784, 2021). "While pro-inflammatory immunocytes, including MOG-35-55-specific T cells, exacerbate stroke, alternatively activated macrophages and microglia provide a critical balance for regulating inflammation and tissue repair." (PMID 30683115, 2019). "Recently, in brain slices from 5 patients with acute middle cerebral artery ischemic stroke, who died within 7–10 days after stroke onset, T cells, including MOG-specific CD4+ T cells were found in the infarct and peri-infarct area close to ischemic neurons." (PMID 31001280, 2019). "Accordingly, the induction of MBP-induced or MOG-induced tolerance was found to prevent CNS autoimmunity and improve outcomes in experimental stroke." (PMID 29422904, 2018). "Increased influx of MOG-specific T cells into the brain was also detected after experimental stroke." (PMID 25309322, 2014). "More importantly for human stroke, RTL1000 (an HLA-DR2 moiety linked to human MOG-35-55 peptide) reduced infarct size and improved behavioral outcomes in humanized DR2 mice." (PMID 24838614, 2014). "Indeed, there is an increase in neural and myelin antigens, including MAP-2, MBP, and MOG, in macrophages, as well as migrated DCs, in the cervical lymph nodes of patients with stroke." (PMID 34335623, 2021). "Brain-derived antigens such as myelin basin protein (MBP), myelin oligodendrocyte glycoprotein (MOG), microtubule-associated protein 2 (MAP2), neurofilament light polypeptide (NF-L) and NMDA receptor subunit (NR-2A) have been observed in the CLNs of both mice and humans after stroke." (PMID 38648267, 2024). "However, nasal MOG tolerization in stroke induced more IL-10 and less CD11b cells than oral MOG." (PMID 25309322, 2014). "Only three studies evaluated the presence of other NSA-Ab seropositivity after stroke, finding very few patients with LGI, CASPR2, myelin, GAD65, MOG and aquaporin-4 antibodies, with a very similar rate in the control group." (PMID 39897448, 2025). "During a stroke, BBB breakdown induces the leakage of oligodendrocyte antigens, such as myelin oligodendrocyte glycoprotein (MOG), and myelin basic protein (MBP) into the periphery." (PMID 32174916, 2020). "In a cohort of 28 patients with milder ischemic stroke, frequencies of MOG and MBP-specific IFN-γ responses, that were measured in peripheral blood, were increased early within the first week after stroke and decreased at 3 months." (PMID 31001280, 2019). "Importantly, taking myelin oligodendrocyte glycoprotein (MOG) through the nose triggers Il-10 secretion from CD4+ T cells, which helps reduce stroke-related disability." (PMID 36793730, 2023).
Encephalopathy (20 papers, 2011 to 2024). Encephalopathy is a term that means brain disease, damage, or malfunction. "Antibodies against the N-methyl-D-Aspartate receptor (NMDA-R-IgG) are the most commonly encountered in association with MOG-IgG, and patients typically present with encephalopathy, seizures, and leptomeningeal enhancement." (PMID 35785363, 2022). "Encephalopathy at onset is associated more frequently with MOG Ab+ children with higher sNfL levels and MOG titer." (PMID 34867740, 2021). "In the current study, we further demonstrated that in ADS MOG-Ab+ children, encephalopathy is associated with higher sNfL levels and a trend for higher MOG titer." (PMID 34867740, 2021). "Visual impairment (30%) was second only to encephalopathy among the first symptoms experienced by the MOG-Ab-positive children." (PMID 36401212, 2022). "In the MOG-Ab-positive group, five children relapsed, one of whom initially showed symptoms of ON, such as visual impairment, before showing symptoms of encephalopathy after recurrence." (PMID 36401212, 2022). "Thirty-five patients (21 males and 14 females) in the MOG-IgG-positive group with encephalopathy, multifocal neurological symptoms, and typical magnetic resonance imaging (MRI) abnormalities were enrolled." (PMID 36352355, 2022). "About 53% of MOG-Ab+ patients presented encephalopathy at onset, but only in 1/22 of MOG-Ab– patients (p = 0.0006)." (PMID 34867740, 2021). "In our registry of patients with IIDDs, MOG-IgG positive patients with seizures and/or encephalopathy were also observed." (PMID 31080435, 2019). "We investigated the clinical features of MOG-IgG positive patients presenting with seizures and/or encephalopathy in a single cohort." (PMID 31080435, 2019). "In the seizures and/or encephalopathy group, MOG-IgG titers were significantly higher at the nadir stage compared with last follow-up." (PMID 31080435, 2019). "In the seizures and/or encephalopathy group, the MOG-IgG titer at the peak stage was positive related with EDSS score at last follow-up." (PMID 31080435, 2019). "Subgroup analysis showed that 30% (7/23) MOG-IgG positive subjects with seizures and/or encephalopathy had been misdiagnosed for central nervous system infection on the basis of meningoencephalitis symptoms and elevated CSF leukocytes (P = 0.002)." (PMID 31080435, 2019). "In the present study, we investigated the clinical profiles of MOG-IgG positive patients with seizures and/or encephalopathy." (PMID 31080435, 2019). "We found that seizures and/or encephalopathy were commonly seen in pediatric and young adult patients with MOG-IgG, often complicating with a relapsing disease course." (PMID 31080435, 2019). "About 53% of MOG-Ab+ presented encephalopathy at onset, 1/22 of MOG-Ab– (p = 0.0006)." (PMID 34867740, 2021). "To summarize, MOG-IgG positive ADEM frequently occurred in winter and spring, and its main clinical manifestations are encephalopathy and multifocal neurologic signs, usually with good prognosis, while some suffered from mild neurological sequelae." (PMID 36352355, 2022). "The sNfL levels were compared in MOG-Ab+/MOG-Ab– and in two subgroups MOG-Ab+ with/without encephalopathy." (PMID 34867740, 2021). "Comparison of baseline demographic and laboratory features between MOG-Ab positive (+) ADS with encephalopathy and MOG-Ab positive (+) ADS without encephalopathy." (PMID 34867740, 2021). "In this study, in a cohort of 37 children with the first event of ADS, we tested sNfL levels in MOG-Ab+ and MOG-Ab– patients, and in two subgroups of MOG-Ab+ subdivided into those with and without encephalopathy." (PMID 34867740, 2021). "Nevertheless, studies with detailed description of the clinical, radiological, laboratory characteristics, and disease course of MOG-IgG positive patients with seizures and/or encephalopathy are lacking." (PMID 31080435, 2019). "Comparison of clinical features between MOG-IgG positive subjects with or without seizures and/or encephalopathy." (PMID 31080435, 2019).
Encephalopathy (continued). "Comparison of CSF features between MOG-IgG positive patients with or without seizures and/or encephalopathy." (PMID 31080435, 2019). "Several observational studies with small sample sizes reported the presence of seizures ranged from 14.70 to 36.36% in MOG-IgG positive patients, and the main symptoms were generalized seizure with or without encephalopathy." (PMID 31080435, 2019). "Comparison of MRI features between MOG-IgG positive patients with or without seizures and/or encephalopathy." (PMID 31080435, 2019). "Moreover, these patients had a correlation between disease condition and MOG-IgG antibody titer which was the same as the counterparts who did not experience seizures or encephalopathy." (PMID 31080435, 2019). "Subjects with MOG-IgG seropositivity were analyzed according to whether they presented with or without seizure and/or encephalopathy." (PMID 31080435, 2019). "Additionally, 18% of children presenting with polyfocal acute demyelinating disease without encephalopathy had MOG antibodies." (PMID 31163654, 2019). "We evaluated the longitudinal changes in serum MOG-IgG titres during the remission phase at the last follow-up in 17 (73.9%) subjects who had seizure and/or encephalopathy and 14 (40.0%) subjects not experiencing these symptoms; MOG-IgG titer decreased 65% and 57% in the two groups, respectively." (PMID 31080435, 2019). "Overall, we recruited 58 subjects seropositive for MOG-IgG and seronegative for AQP4-IgG, including 23 (39.7%, 23/58) subjects with seizures and/or encephalopathy and 35 subjects without seizures or encephalopathy." (PMID 31080435, 2019).
papillitis (20 papers, 2019 to 2025). "In contrast, an acute primary MOG-IgG/CD4 + T-cells-related longitudinal inflammation of the distal optic nerve causes a global perineural contrast enhancement with papilledema and equal affection of all ON fibers in MOGAD." (PMID 39249105, 2024). "MOG-associated ON mainly affected the anterior part of the optic nerve with a papilledema in 79.2% of cases." (PMID 34097296, 2022). "The anterior part of the optic nerve was preferentially injured in anti-MOG neuritis with 19/25 ON associated with papilledema on the fundus examination." (PMID 34097296, 2022). "Demonstration of papillitis/papilledema and/or retinal hemorrhages renders MOG-EM/MOGAD more likely than NMOSD and MS, in which optic disk edema is both less frequent and, usually, less severe." (PMID 37022481, 2023). "On the other hand, atypical features, such as prominent optic disc edema, poor treatment response, and bilateral involvement are often associated with autoantibodies against aquaporin-4 (AQP4) and Myelin Oligodendrocyte Glycoprotein (MOG)." (PMID 37958968, 2023). "The most common papillitis are idiopathic, demyelinating, and antibody-mediated (aquaporin-4 and antimyelin oligodendrocyte glycoprotein (MOG))." (PMID 37987292, 2023). "In contrast, these mechanisms seem to be less relevant for MOGAD-ON, while a massive acute primary MOG-IgG related inflammation involves all distal parts of the optic nerve, additionally resulting in a papilledema and often more severe retroorbital pain." (PMID 35869995, 2022). "MOG-ON had a higher rate of optic disk edema than the ION and AQP4-ON groups, which corresponded to the results of our previous studies." (PMID 36507533, 2022). "MOG-ON had a higher rate of optic disk edema than ION and AQP4-ON (83.3 vs. 61.9%, p = 0.019 and 83.3 vs. 25.9%, p = 0.016, respectively)." (PMID 36507533, 2022). "Optic nerve lesions, papillitis, myelin oligodendrocyte glycoprotein (MOG) positive antibodies, and perineuritis are consistent with ON." (PMID 34842783, 2021). "Myelin oligodendrocyte glycoprotein-associated disease (MOGAD) has a wide phenotypic expression and should be considered in a differential diagnosis of patients with optic disc edema and increased intracranial pressure because MOGAD can mimic IIH and compressive optic neuropathy." (PMID 38350984, 2024). "Like MOG-ON, these patients may also present with bilateral optic disc oedema with normal CSF opening pressures, though the mechanism in this scenario is thought to be related to primary venulitis with prominent vascular leakage." (PMID 38783085, 2024). "Patients with bilateral papillitis relapsing ON who show steroid dependency in the absence of the AQP4-Ab must be tested for MOG-IgG." (PMID 39692830, 2025). "In addition, the clinical presentation with subacute onset, absent optic disc edema and APD, and minimal contrast enhancement on imaging was incongruent with MOG-associated disease." (PMID 39149664, 2024). "Interestingly, papillitis was recently shown to be common in patients positive for MOG-IgG, a marker not yet tested in patients diagnosed with MDS." (PMID 30819213, 2019).
systemic lupus erythematosus (20 papers, 2011 to 2025). An autoimmune multi-organ disease typically associated with vasculopathy and autoantibody production. "A higher percentage of AQP4-ON patients had comorbidities such as Sjögren’s syndrome and systemic lupus erythematosus compared to MOG-ON patients (6/20 [30.0%] vs. 0/26[0.0%]; p = 0.004)." (PMID 38988608, 2024). "In our study, three MOG-ON patients were either pregnant or postpartum, while one AQP4-ON patient was in the postpartum period and had a history of systemic lupus erythematosus." (PMID 38988608, 2024). "It was demonstrated that immunization of systemic lupus erythematosus (SLE)-prone MRL-lpr/lpr mice with DNA–protein complexes as well as C57BL/6 mice with DNA–histone complexes and MOG results in an acceleration of SLE and EAE development." (PMID 36012448, 2022). "By contrast, 11 further samples from 11 patients with CNS symptoms and systemic lupus erythematosus or other connective tissue disorders included in groups I and IV were negative for MOG-IgG." (PMID 27788675, 2016). "Additional investigation for autoimmune antibodies including antinuclear antibody (ANA), lupus double-stranded DNA, Sjogren’s anti-Ro (SS-A) and anti-La (SS-B), neuromyelitis optica (NMO), and myelin oligodendrocyte glycoprotein (MOG) were nonrevealing." (PMID 39697943, 2024). "Systemic lupus erythematosus, Sjögren syndrome, and myasthenia gravis, which are common in AQP4-IgG-positive NMOSD, were absent in all of our MOG-IgG-positive patients." (PMID 27793206, 2016).
Ataxia (19 papers, 2014 to 2025). Ataxia refers to impaired coordination of voluntary muscle movement. "This is often necessary for the treatment of symptoms, e.g. tremor, ataxia, nystagmus or bladder dysfunction, and even standard when it comes to the first-line immunotherapy of neuromyelitis optica spectrum diseases and MOG-antibody-associated diseases." (PMID 34362474, 2021). "Although two large retrospective studies in adults [22•, 41] and one small retrospective study in children with MOG-Ab and ON demonstrated favorable visual outcome, patients with MOG-Ab can manifest with severe visual loss and permanent paresis or ataxia." (PMID 30671648, 2019). "Although MOG antibody-associated pure cerebellar ataxia with normal imaging is exceptionally rare, it may constitute a distinct phenotype meriting inclusion in the differential diagnosis of childhood acute ataxia, particularly in recurrent cases." (PMID 41321459, 2025). "Neuromyelitis optica spectrum disorders (NMOSD) with AQP-4 antibodies as well as MOG-antibody associated diseases (MOGAD) may present with ataxia." (PMID 39735552, 2024). "Among the patients with anti‐MOG abs, Patient 1 was a 3‐year‐old male who developed ataxia, aphasia, reduced level of consciousness, and RSE." (PMID 40318023, 2025). "MOG IgG antibodies represent prevalent autoantibodies beyond OCBs, including rare presentations of isolated cerebellar ataxia." (PMID 41321459, 2025). "As MOG, AQP-4, KLHL11, and GluK2 antibodies have been identified in NMDAR-E patients and have been associated with neurological symptoms including ataxia, we tested available sera for all four antibodies." (PMID 39735552, 2024). "In more than half of our patients with NMDARE-associated ataxia, we were able to exclude the presence of MOG, AQP-4, KLHL11, and GluK2 antibodies, all of which have previously been associated with both NMDAR-E and CNS neurological deficits including ataxia." (PMID 39735552, 2024). "In contrast, MOG-GP mice developed ascending hind limb paresis and ataxia which persisted during the entire observation period of 4 weeks, while virus was as rapidly cleared as in WT mice within 10 days after i.c. infection." (PMID 33579927, 2021). "In this study, MOG-IgG seropositive children had significantly more ataxia (p = 0.025)." (PMID 35669399, 2022). "Butyrophilin is a dairy compound structurally similar to a compound in the brain, myelin oligodendrocyte glycoprotein (MOG), which through molecular mimicry may lead to immune mediated damage to myelin and neurons thus increasing risk of MS, cerebellar ataxia and neuropsychiatric symptoms." (PMID 30736445, 2019). "We identified 14 MOG IgG antibody-positive cases, including 11 with ADEM and three with isolated cerebellar ataxia (two with relapsing courses)." (PMID 41321459, 2025). "The common clinical manifestations in the MOG-AD and autoimmune GFAP-A groups were fever, consciousness disturbance, seizures, visual disturbance, speech disorder, headache and ataxia." (PMID 37153594, 2023). "In all five patients with cerebellar ataxia tested, MOG, AQP-4, GluK2, and KLHL11 antibodies were negative." (PMID 39735552, 2024). "A higher frequency of ataxia was found in children with ADEM positive for MOG-IgG compared to MOG-IgG negative cases." (PMID 38333186, 2023). "Ataxia is the most common clinical presentation in pediatric ADEM and MOG-abs." (PMID 33329345, 2020). "Patients positive for MOG-abs presented with significantly more ataxia (P = 0.025) and less bladder/rectum dysfunction (P = 0.035) and paralysis (P = 0.04) than patients without MOG-abs." (PMID 33329345, 2020). "Children with ADEM and MOG-abs presented with increased ataxia, reduced bladder/rectum dysfunction, and paralysis compared to children without MOG-abs." (PMID 33329345, 2020). "An interesting finding was that children with MOG-abs presented with increased ataxia and less bladder/rectum dysfunction and paralysis at symptom onset compared to children without MOG-abs." (PMID 33329345, 2020).
Ataxia (continued). "Ataxia is a common clinical manifestation in children with ADEM and MOG-abs." (PMID 33329345, 2020). "In a passive transfer model with MOG-specific T cells derived from 2D2 mice, it was shown that both Th1/Th17 cells are able to induce EAE; however, Th17 induce an atypical phenotype in half the cases (beginning with ataxia instead of paralysis, only developing paralysis later)." (PMID 38333186, 2023). "Nearly 60% of MOG-immunized mice specifically lacking Rheb in T cells developed “nonclassical EAE,” a neurological disorder associated with MOG-specific Th2 cells and characterized by ataxia (not paralysis) and infiltration of the cerebellum with cells of the immune response." (PMID 32377533, 2020). "Serum was tested negative for MOG, AQP-4, KLHL11, and GluK2 antibodies in five of eight patients with cerebellar ataxia (Cases 3–5, 7, and 8)." (PMID 39735552, 2024). "Regarding clinical characteristics, 40% of children with MOG-IgG seropositive ADEM were presented with ataxia, while 32% of children with MOG-IgG seronegative ADEM had ataxia; the difference was not statistically significant." (PMID 35669399, 2022).